OSBPL11 (oxysterol binding protein like 11)
Description:
Plays a role in regulating ADIPOQ and FABP4 levels in differentiating adipocytes and is also involved in regulation of adipocyte triglyceride storage. Weakly binds 25-hydroxycholesterol. Interacts with OSBPL9 to function as lipid transfer proteins. Together they form a heterodimer that localizes at the ER-trans-Golgi membrane contact sites, and exchanges phosphatidylserine (1,2-diacyl-sn-glycero-3-phospho-L-serine, PS) for phosphatidylinositol-4-phosphate (1,2-diacyl-sn-glycero-3-phospho-(1D-myo-inositol 4-phosphate), PI(4)P) between the two organelles, a step that is critical for sphingomyelin synthesis in the Golgi complex.
Synonyms: ORP-11; ORP11; OSBP12; FLJ13012; FLJ13164; TCCCIA00292
Tractability: PROTAC: ubiquitination databases record sites on it; its protein half-life has been measured.
Gene: Protein-coding gene on chromosome 3 (125,528,858 to 125,595,592, reverse strand). Ensembl gene ENSG00000144909.
Subcellular location: Late endosome membrane; Golgi apparatus, trans-Golgi network membrane
Subcellular location (Human Protein Atlas): Golgi apparatus; Nucleoplasm
Pathways (Reactome):
Signal Transduction: RHOH GTPase cycle
Gene Ontology:
Molecular function: phosphatidylserine-phosphatidylinositol-4-phosphate exchange activity; protein binding; lipid binding
Biological process: fat cell differentiation; lysosomal membrane organization; phospholipid homeostasis; phospholipid transfer to membrane; triglyceride homeostasis; intermembrane lipid transfer
Cellular component: endoplasmic reticulum-trans-Golgi network membrane contact site; lysosomal membrane; trans-Golgi network; cytosol; Golgi apparatus; membrane; late endosome membrane
Genetic constraint (gnomAD): Loss-of-function variants: 25 observed, 72.68 expected, observed/expected ratio (o/e) 0.34, 90% interval 0.25 to 0.48. The upper end of that interval is the gene's LOEUF score, 0.48, which puts it in group 2 of 6, group 1 being the genes least tolerant of losing a copy. Missense variants: 684 observed, 877.49 expected, observed/expected ratio (o/e) 0.78, 90% interval 0.73 to 0.83. Synonymous variants: 263 observed, 305.53 expected, observed/expected ratio (o/e) 0.86, 90% interval 0.78 to 0.95.
Homologues: Orthologues: chimpanzee OSBPL11 (99% identical), macaque OSBPL11 (96% identical), pig OSBPL11 (96% identical), mouse Osbpl11 (92% identical), rat Osbpl11 (92% identical), rabbit OSBPL11 (92% identical), guinea pig OSBPL11 (76% identical), tropical clawed frog osbpl11 (71% identical), zebrafish osbpl11 (65% identical), Drosophila melanogaster CG3860 (13% identical), Caenorhabditis elegans obr-2 (11% identical). Paralogues in human: OSBPL10 (55% identical), OSBPL9 (38% identical), OSBPL5 (23% identical), OSBPL8 (23% identical), OSBPL6 (19% identical), OSBPL7 (19% identical), OSBP2 (18% identical), OSBPL1A (18% identical), OSBP (18% identical), OSBPL3 (18% identical), OSBPL2 (13% identical).
Diseases named in the same sentence as OSBPL11 in open-access papers:
OSBPL11 is named in the same sentence as 21 diseases in open-access papers, as found by Europe PMC text mining. Sharing a sentence is not in itself a finding about the gene and the disease. The quoted sentences say what the papers report.
metabolic syndrome (3 papers, 2012 to 2025). A cluster of metabolic risk factors for CARDIOVASCULAR DISEASES and TYPE 2 DIABETES MELLITUS. "OSBPL11 belongs to a group of intracellular lipid receptors and polymorphisms have been associated with T2DM in humans and components of the metabolic syndrome." (PMID 26606528, 2015).
acute myeloid leukemia (2 papers, 2022 to 2023). Acute myeloid leukemia (AML) is a group of neoplasms arising from precursor cells committed to the myeloid cell-line differentiation. "It has been reported that exosomal miR-7-5p derived from BMSCs could negatively regulate OSBPL11 via PI3K/AKT/mTOR signaling pathway in acute myeloid leukemia (AML) and finally inhibit AML proliferation and promote apoptosis." (PMID 35300408, 2022).
Hyperglycemia (2 papers, 2025). An increased concentration of glucose in the blood. "SNPs in ORP7, OSBPL11, and OSBPL10 have been linked to LDL-C levels, hyperglycemia, and cardiovascular risk factors." (PMID 40716750, 2025).
Obesity (2 papers, 2015 to 2025). Accumulation of substantial excess body fat. "In humans, elevated expression of OSBPL11 in adipocytes has been associated with conditions related to overnutrition, such as obesity and other diseases of metabolism." (PMID 40492082, 2025). "In addition to MAP2K3-B and PPARG2, autoantibodies to OSBPL11, CBS and TAL were also associated with cases and may be relevant to the pathophysiology of T2DM or obesity." (PMID 26606528, 2015).
Hypertension (1 paper, 2025). The presence of chronic increased pressure in the systemic arterial system. "The lead variant in the OSBPL11 loci was also associated with triglyceride levels, LDL cholesterol, fat mass, BMI, hypertension and stroke in African ancestry populations." (PMID 40492082, 2025). "Moreover, the association between the lead variant in OSBPL11 and cardiometabolic traits, such as triglyceride levels, fat mass, BMI, hypertension, and stroke, suggests a role of OSBPL11 in lipid metabolism." (PMID 40492082, 2025).
pancreatic carcinoma (1 paper, 2021). "The data demonstrated that OSBPL3, OSBPL8, OSBPL10, and OSBPL11 were overexpressed in pancreatic cancer tissues." (PMID 34829830, 2021). "for OSBPL11, there was an increase in pancreatic carcinoma with a multiple of change of 1.509." (PMID 34829830, 2021).
tumor (1 paper, 2023). "As to the protein expression, OSBPL2 and OSBPL3 were significantly elevated and OSBPL5, OSBPL6, OSBPL9, OSBPL10, OSBPL11 were downregulated in tumor samples." (PMID 36918840, 2023). "The results demonstrated that the protein expressions of OSBPL2 and OSBPL3 were elevated while OSBPL5, OSBPL6, OSBPL9, OSBPL10, and OSBPL11 were lowly expressed in tumor samples." (PMID 36918840, 2023).
OSBPL11 also shares sentences with these, for which no sentence is quoted: cancer (2 papers); cardiac disease (1); colon cancer (1); diabetes (1); glaucoma (1); malaria (1); metabolic disorders (1); myotonic dystrophy type 1 (1); of metabolism (1); osteogenesis imperfecta (1); overnutrition (1); Stroke (1); Treacher-Collins syndrome (1); tuberculosis (1).